BMP6 (bone morphogenetic protein 6)
Diseases named in the same sentence as BMP6 in open-access papers (continued):
Sharing a sentence is not in itself a finding about the gene and the disease.
breast tumor (4 papers, 2007 to 2023). "In 33 breast tumour specimens, hypermethylation of BMP-6 was observed in all ER-negative cases whereas lower methylation frequency was observed in ER positive cases." (PMID 28733469, 2017). "The effects of 1,25(OH)2D3 0.5nM on the expression of CYP24A1, DPP4, IL1RL1, CD14, CA2 and BMP6, were further explored in breast tumor derived cells, representing the epithelial and stromal compartments, using RT-qPCR." (PMID 23497279, 2013). "Repressors of BMP-6 and E-cadherin, such as δEF1, may regulate breast tumor progression and metastasis at different stages, including the initial de-differentiation of primary tumor cells and the maintenance of migratory and/or undifferentiated phenotypes." (PMID 17997862, 2007). "In addition, our results revealed that expression of BMP-6 in ER+ breast tumor specimens was comparatively higher than in ER- cases." (PMID 17997862, 2007).
colorectal cancer (4 papers, 2017 to 2024). A primary or metastatic malignant neoplasm that affects the colon or rectum. "Knocking down GREM1 activates PI3K/AKT phosphorylation and promotes macrophage M2 polarization by increasing BMP6 expression, thus promoting the proliferation and migration of colorectal cancer in vitro and promoting the occurrence of liver metastasis of colorectal cancer in vivo." (PMID 38970064, 2024). "For investigate the expression of miR-455、GREM1 and BMP6 in colorectal cancer, we collected LM tissues, PT tissues and PC tissues of colorectal cancer of 5 patients for qRT-PCR and western blotting detection from the First Affiliated Hospital of Nanjing Medical University." (PMID 38970064, 2024). "Expression of BMP2, BMP4, BMP5, BMP6, BMP9 and osteocalcin has been reported in colorectal cancer with heterotopic ossification." (PMID 29029440, 2017).
endometriosis (4 papers, 2022 to 2025). The growth of functional endometrial tissue in anatomic sites outside the uterine body. "In forest plots, the overall effect sizes of SNPs for BMP6 and SLC48A1 were positioned to the right of zero, further suggesting their contribution to endometriosis susceptibility." (PMID 41150779, 2025). "In scatter plots, the positive slopes of the IVW algorithm indicated that BMP6 and SLC48A1 increased endometriosis risk." (PMID 41150779, 2025). "We focused on the roles of BMP/SMAD1/5 signaling given that we observed altered expression of BMP ligands (BMP4, BMP6) as well as decreased expression of canonical SMAD1/SMAD5 targets in the decidualizing stromal cells from individuals with endometriosis." (PMID 38402336, 2024). "In infertile women with endometriosis, the expression of the BMP6 gene is relatively reduced." (PMID 35456401, 2022). "Previous studies also suggest that BMP6 modulates granulosa cell function, affects steroid hormone synthesis, and participates in neutrophil accumulation and regulation within the ovary, potentially promoting endometriosis progression through crosstalk with estrogen signaling." (PMID 41150779, 2025). "BMP6 and SLC48A1 were significantly upregulated in endometriosis samples compared with controls in both the training and validation sets (p < 0.05)." (PMID 41150779, 2025). "RT-qPCR confirmed elevated expression of BMP6 and SLC48A1 in endometriosis samples relative to controls." (PMID 41150779, 2025). "The biomarkers BMP6 and SLC48A1 demonstrated significantly elevated expression in endometriosis samples, a finding consistently validated through both bioinformatics and RT-qPCR analyses." (PMID 41150779, 2025). "Both BMP6 and SLC48A1 were consistently overexpressed in endometriosis, reinforcing their potential as biomarkers." (PMID 41150779, 2025). "The RT-qPCR results were consistent with the bioinformatics analyses, confirming that BMP6 and SLC48A1 were differentially expressed between the endometriosis and control groups." (PMID 41150779, 2025). "Furthermore, the Steiger test was TRUE for both genes, demonstrating the absence of reverse causality between BMP6, SLC48A1, and endometriosis." (PMID 41150779, 2025). "The exposure levels of BMP6 and SLC48A1 were shown to affect endometriosis, while endometriosis did not exert a reverse effect on the expression of BMP6 and SLC48A1." (PMID 41150779, 2025). "BMP6 exhibited the strongest negative correlation with monocytes, whereas SLC48A1 demonstrated the strongest positive correlation with activated NK cells, suggesting their involvement in endometriosis through immune cell regulation." (PMID 41150779, 2025).
haemochromatosis (4 papers, 2021 to 2024). "In our study, application of GREEN-DB led to identification of candidate variants in several cases including a deep intronic variant in BMP4 in a patient with Kapur-Toriello syndrome and variants in HSD3B7 and BMP6 in a patient with neonatal haemochromatosis." (PMID 37946251, 2023). "HJV is essential for BMP6 signalling because the disruption of the protein, as occurs in the juvenile form of the iron loading disorder, haemochromatosis, leads to the complete loss of hepcidin production." (PMID 34611951, 2021). "Also, BMP6 regulates liver iron homeostasis and reduced BMP6 levels resulting from germline mutations underlie some cases of haemochromatosis." (PMID 35434863, 2023). "BMP6 was also shown to be one of the key regulators of hepcidin expression and iron metabolism, and BMP6−/− displayed a phenotype similar to hereditary hemochromatosis." (PMID 39063084, 2024).
heart failure (4 papers, 2019 to 2025). Inability of the heart to pump blood at an adequate rate to meet tissue metabolic requirements. "Our MR analysis, akin to this finding, revealed that BMP6 acts as a protective factor against DCM-related heart failure." (PMID 39825396, 2025). "Although a clinical study showed increased circulating levels of BMP6 in patients with advanced heart failure, information on the regulation and role of BMP6 in the infarcted myocardium is lacking." (PMID 31620450, 2019). "The levels of BMP6 protein expression were elevated in patients with advanced heart failure, indicating that BMP6 is a promising cardiac marker to predict heart failure and a possible protective factor to the various subsequent cardiac pathophysiological changes following heart failure." (PMID 37313693, 2023). "This is also supported by high levels of BMP6 in patients with advanced heart failure." (PMID 36553589, 2022). "Bulk RNA-seq, single-cell RNA-seq, Mendelian randomization analysis, animal model construction, and BMP6 knockdown were utilized to identify and validate potential specific markers and targets for intervention in DCM heart failure." (PMID 39825396, 2025).
liver cancer (4 papers, 2019 to 2025). An epithelial or non-epithelial malignant neoplasm that arises from the liver. "In another model of rat liver cancer after long-term feeding of choline-deficient/L-amino acid-defined diet, BMP6 expression was also significantly reduced in liver cancers compared to normal liver tissues." (PMID 34277457, 2021). "To further elucidate the significance of BMP6 downregulation in liver cancers, we analyzed BMP6 expression levels in experimental liver cancer models due to Tnixp gene deficiency." (PMID 34277457, 2021). "BMP6/IL6 pathway insufficiency is a potential cause of hepcidin downregulation in liver cancers." (PMID 34277457, 2021). "Similar findings were obtained in HCC tissues from female p53LKO mice: high TfR1 and low mRNA expression of Hamp, Hfe, Smad7, Bmp6, and Ferroprotin (Fpn1), were observed in liver cancer tissues in comparison to NTL." (PMID 39820815, 2025). "There was only one study showing a reduced BMP6 expression due to BMP6 promoter hypermethylation in human liver cancer tissues." (PMID 34277457, 2021). "BMP6 expression was significantly reduced in liver cancers of Tnixp-mutant mice, which is in parallel with hepcidin reduction." (PMID 34277457, 2021). "Hepcidin expression in liver cancer tissues positively correlated with the bone morphogenetic protein-6 (BPM6)/interleukin-6 (IL6) cytokines and cytotoxic immune infiltration." (PMID 34277457, 2021). "Altogether, our results indicate that BMP6/HAMP insufficiency might be an important factor in liver cancer development or progression." (PMID 34277457, 2021). "Furthermore, hepcidin expression was tightly associated with BMP6 proteins and IL6 cytokines, as well as anti-cancer immune infiltration in liver cancer tissues." (PMID 34277457, 2021). "A few studies suggest that BMP6 and HJV, which are inhibited in liver cancer, are the main regulator of hepcidin expression, while studies have also shown that the low expression of hepcidin predicts poor prognosis in liver cancer patients." (PMID 31052210, 2019).
melanoma (4 papers, 2022 to 2025). A malignant, usually aggressive tumor composed of atypical, neoplastic melanocytes. "For example, BMP6, showed high expression in melanoma cells and tissues, and the BMP6 deficiency in mice could lead to delayed melanoma tumor onset and decelerated tumor progression." (PMID 36777724, 2023). "Finally, Bmp6 deficiency in a mouse model of melanoma was linked with a large reduction in tumor progression." (PMID 35163468, 2022). "Research indicates that increased BMP6 expression in melanoma cells can modulate the tumor milieu by inhibiting dermal mast cell recruitment, which in turn affects tumor progression." (PMID 40642086, 2025). "Moreover, the RNF4~BMP6~RGMBP axis is critical for the survival of aggressive bone cancers and melanoma and is associated with poor prognosis of sarcoma patients." (PMID 36153321, 2022). "Moreover, BMP6 has been implicated in the TME, particularly in melanoma." (PMID 40642086, 2025). "Then, we identified 9 LR pairs (“BMP6- > HJV” 、"CCL8- > ACKR4” 、"DLL3- > NOTCH3"、"DSC3- > DSG3"、"GHRH- > GHRHR” 、"LRRC4B- > PTPRF"、"SEMA4D- > PLXNB1"、"SFRP1- > FZD6"、"UCN- > CRHR1′′) as key LR pairs in melanoma prognosis through Lasso Cox regression and Multiple Stepwise Regression." (PMID 36777724, 2023). "The results showed that the expression of DSC3, DLL3, BMP6, SEMA4D, and GHRH are increased (p < 0.05) in melanoma, while the expression of LRRC4B, SFRP1, DCN, and CCL-8 decreased in melanoma (p < 0.05)." (PMID 36777724, 2023).
non-alcoholic fatty liver disease (4 papers, 2020 to 2025). "Hepatoprotective effects of BMP6 have been described in non-alcoholic fatty liver disease, indicating an association of BMP6 with metabolism." (PMID 39200147, 2024). "In this regard, murine hepatocytes produced BMP6 in an in vitro model of cellular lipid accumulation and hepatocytes were identified as a cellular source of hepatic BMP6 in livers of patients with non-alcoholic fatty liver disease." (PMID 39827450, 2025). "Recombinant BMP6 has anti-inflammatory activities, exerts anti-fibrotic effects in hepatic stellate cells, and was protective in a murine model of non-alcoholic fatty liver disease." (PMID 39200147, 2024). "Murine hepatocytes were reported to produce BMP6 in an in vitro model of cellular lipid accumulation and hepatocytes were identified as cellular source of hepatic BMP6 in livers of patients with non-alcoholic fatty liver disease." (PMID 32998264, 2020).
non-small cell lung carcinoma (4 papers, 2005 to 2022). A group of at least three distinct histological types of lung cancer, including non-small cell squamous cell carcinoma, adenocarcinoma, and large cell carcinoma. "Concurrent epigenetic inactivation of BMP3 and BMP6 was shown to be associated with the hyperactivation of the RAS-RAF-MEK-ERK signaling pathway in non-small-cell lung cancer." (PMID 20027224, 2009). "We investigated whether BMP6 is epigenetically inactivated in cell lines and whether BMP3b and BMP6 are epigenetically inactivated in non-small-cell lung cancer (NSCLC)." (PMID 16175182, 2005).
Obesity (4 papers, 2014 to 2025). Accumulation of substantial excess body fat. "In conclusion, a combination of upregulated obesity-related CVRPs (ANGPT1, IL, 1Ra, XCL1) and downregulated cardioprotective proteins (sRAGE, BMP6, Mn-SOD, GDF2) in PCOS may contribute to the increased risk of CVDs in overweight women with PCOS." (PMID 39858399, 2024). "BMP6 might serve as a novel therapeutic for obesity by enhancing the amount of myogenic lineage-derived BAT." (PMID 34258293, 2021). "BMP2, BMP4, BMP6, BMP7, and BMP9 have been shown to affect the pathophysiological process of obesity and glucose metabolism beyond bone metabolism." (PMID 34258293, 2021).
osteoarthritis (4 papers, 2006 to 2025). A noninflammatory degenerative joint disease occurring chiefly in older persons, characterized by degeneration of the articular cartilage, hypertrophy of bone at the margins and changes in the synovial membrane. "Furthermore, the expression of BMP-6 and BMP-7 was also decreased in articular cartilage of TNF-transgenic mice, suggesting that loss of BMP expression could be also involved in chronic inflammatory and not only degenerative joint diseases." (PMID 16542506, 2006). "We evaluated the safety and efficacy of recombinant human BMP6 (rhBMP6) applied within an autologous blood coagulum (ABC) in a surgically created wedge defect of the proximal tibia in patients undergoing high tibial osteotomy (HTO) for varus deformity and medial osteoarthritis of the knee." (PMID 32543706, 2020).
psoriasis (4 papers, 2016 to 2024). An autoimmune condition characterized by red, well-delineated plaques with silvery scales that are usually on the extensor surfaces and scalp. "HIF-1α inhibited expression of BMP6 by binding to the HRE of promoter of BMP6, thereby aggravating the pathological features in psoriasis." (PMID 36761171, 2022). "Another study reported that HIF1α aggravates psoriasis by inhibiting BMP6 expression." (PMID 38491188, 2024).
rheumatoid arthritis (4 papers, 2005 to 2020). A chronic, systemic autoimmune disorder characterized by inflammation in the synovial membranes and articular surfaces. "Moreover, BMP-6 has been suggested to play a role in rheumatoid arthritis (RA) and elevated levels of Id1 and Id3 have been found in the synovia of RA-patients." (PMID 15877825, 2005). "In patients with rheumatoid arthritis, stimulation with IL-1β induced BMP-2 and BMP-6, but not BMP-4, BMP-5, or BMP-7 in fibroblast-like synoviocytes." (PMID 32290085, 2020).
age-related macular degeneration (3 papers, 2020 to 2022). Age-related loss of vision in the central portion of the retina (macula), secondary to retinal degeneration. "BMP6 also regulates retinal iron homeostasis, and its altered expression may contribute to iron accumulation in age-related macular degeneration." (PMID 36230892, 2022). "H2O2 increased iron concentration in retinal pigment epithelial cells via the BMP6/SMAD/hepcidin axis, resulting in age-related macular degeneration.Inhibitory SMAD7 is a key repressor of hepcidin, the master regulator of systemic iron homeostasis." (PMID 36398315, 2022). "A reduction in the levels of BMP6 has been reported in neovascular and early age-related macular degeneration (AMD) In-vitro studies have shown that BMP6 may protect the retinal pigment epithelial (RPE) cells from oxidative stress and apoptosis." (PMID 32641001, 2020). "BMP6 is also expressed by retinal pigment epithelial (RPE) cells, and its downregulated expression in age-related macular degeneration (AMD) likely contributes to iron build up in AMD." (PMID 36230892, 2022).
Arthritis (3 papers, 2009 to 2022). Inflammation of a joint. "In addition, it is important to note that from our in-silico analysis, we have identified 38 BMP family members; however, we only focused on four genes, namely, BMP2a, BMP4, BMP6, and BMP7b, in a gut inflammation-associated arthritis gene expression study." (PMID 36500396, 2022). "Inhibition of BMP6 prevents the onset and progress of an SpA-type model of arthritis." (PMID 19900269, 2009). "The increased expression and production of specific BMPs (i.e., BMP2, BMP6, and BMP7) in the synovium and synovial fluid of patients with RA as well as in mouse models of arthritis have been reported by different groups." (PMID 26215036, 2015). "Several BMP ligands, including BMP2, BMP6, and BMP7, have been shown to be upregulated in the synovium of patients with RA as well as in tumor necrosis factor-alpha (TNF-α) transgenic mice developing arthritis and in collagen-induced arthritis models." (PMID 26215036, 2015).
COVID-19 (3 papers, 2022 to 2024). A disease caused by infection with severe acute respiratory syndrome coronavirus 2. "Plasma BMP6 levels of COVID-19 patients tended to be lower in comparison to the healthy controls (p = 0.097)." (PMID 39200147, 2024). "The 23 COVID-19 patients exhibited plasma BMP6 levels comparable to the sepsis/septic shock patients without a SARS-CoV-2 infection (p = 0.250)." (PMID 39200147, 2024). "Conversely, the BMP and TGFβ signaling pathways showed specific down-regulation in endothelial cells from COVID-19 hearts, including down-regulation of BMPR1A, BMPR1B, SMAD6, and BMP6." (PMID 37830426, 2023). "The remaining post-COVID-19 signature shows good agreement with single-cell RNA sequencing data and contains, among others, proteins related to TGFβ signaling, maintenance of the ECM (TGFβ1, BMP-6, MMP1, MMP7), and TNF-signaling (TNFα, TWEAK)." (PMID 36405747, 2022).
ovarian carcinoma (3 papers, 2019 to 2024). A malignant neoplasm originating from the surface ovarian epithelium. "The expression of HFE, MTF1, and BMP6 involved in iron regulation was associated with improved PFS in ovarian cancer, whereas the expression of HIF1A, GPI, and HAMP involved in this process was associated with poor PFS in ovarian cancer." (PMID 38186569, 2023). "The expression of MTF1 and BMP6 involved in iron regulation was associated with improved OS in ovarian cancer, whereas the expression of IREB2, GPI, and HMOX1 in this process was associated with poor OS in ovarian cancer." (PMID 38186569, 2023). "We found that a low expression level of CDKN2B and WNT11 was associated with longer survival in ovarian cancer patients, while high expression levels of SMAD3, ZFYVE16, BMP6, LEFTY1, and DVL2 were significantly associated with poor survival." (PMID 38403634, 2024). "Exploring the iron regulation in ovarian cancer, most genes integral to this process, like IREB2, HFE, BMP6, HMOX1, and ACO1, showed decreased expression compared to their normal tissue counterparts." (PMID 38186569, 2023). "Additionally, T-MSCs promoted the proportion of CSCs, as observed in ovarian cancer cell, probably because of upregulation of bone morphogenetic proteins (BMPs), such as BMP2, BMP4, and BMP6 in ovarian cancer-derived MSCs." (PMID 31555593, 2019).
prostatic adenocarcinomas (3 papers, 1998 to 2022). "The BMP-6 mRNA appeared to be strongly expressed in prostatic adenocarcinoma both in the primary tumor and in bone metastases." (PMID 31137764, 2019). "BMP-6 mRNA appears to be strongly expressed in prostatic adenocarcinomas, both in the primary tumour and in bone metastases." (PMID 9820184, 1998). "This study examines the expression of BMP-6 mRNA in matched prostatic primary and secondary bony lesions and in isolated skeletal metastases from prostatic adenocarcinomas, as well as other common human malignancies, by in situ hybridization." (PMID 9820184, 1998). "Additionally, a good correlation between elevated BMP-6 expression in prostate adenocarcinoma and osteoblastic metastases is noted." (PMID 36139691, 2022).